SNORA17B (small nucleolar RNA, H/ACA box 17B)
Synonyms: ACA43; formerly SNORA43
Gene: Small nucleolar RNA gene on chromosome 9 (136,726,105 to 136,726,234, reverse strand). Ensembl gene ENSG00000276161.
Gene Ontology:
Biological process: RNA processing
Cellular component: nucleolus
Homologues: Orthologues: chimpanzee SNORA17B (100% identical).